SMAD3 (SMAD family member 3)
Diseases named in the same sentence as SMAD3 in open-access papers (continued):
Sharing a sentence is not in itself a finding about the gene and the disease.
tumor (continued). "For this, we reintroduced increasing amounts of Smad3 in Huh7-shRNA-Smad3 clones and determined in these cells the levels of TGF-β signaling and anti-tumor or pro-tumor responses." (PMID 19190755, 2009). "We suggest that the transcription factors SMAD3/4, GNB2L1/RACK1, MYC, MAX and JUN, whose functions have been extensively studied in tumours but only marginally in muscle, appear instead to play important roles in regulating muscle response to atrophy." (PMID 19108710, 2008). "The difference was not statistically significant between p-Smad3-positive tumor cells in the Anti-PD-1+TR group and the Chemo+TR group." (PMID 40801643, 2025). "Furthermore, following castration surgery in nude mice, subcutaneous implantation of C42B‐ABi cells with stable knockdown of BCL6, SMAD3 and NFIB significantly suppressed tumor proliferation compared to the control group." (PMID 40470696, 2025). "SMAD3 is a key transcription factor downstream of classical TGF-β signaling and plays a pivotal role in the regulation of cell proliferation, apoptosis, differentiation, epithelial–mesenchymal transition, tumor suppression and cancer promotion." (PMID 40721814, 2025). "SMAD3, a key mediator of the TGF-β signaling pathway, demonstrates significant upregulation in advanced-stage LUAD compared with early-stage disease, correlating with increased tumor aggressiveness, invasive capacity, and poor patient outcomes." (PMID 40361382, 2025). "For instance, miR-1 was early characterized as a tumor-suppressive factor in multiple malignancies, demonstrating its negative role on cell proliferation and migration through the targeting of key genes such as LASP1 and Smad3." (PMID 40871106, 2025). "Myeloid-specific Smad3 overexpression promotes the differentiation of MO-MDSC into mature MΦ and DC, enhances MHC-II expression, and reduces immunosuppressive molecules, thereby attenuating tumor progression." (PMID 41360769, 2025). "We analyzed the relationship between tumor‐infiltrating immune cells (CD4, CD8, FOXP3, CD163‐positive cells) and proteins (TGFβ1 and its downstream signal, SMAD3) expression and survival after the start of combined therapy with immune checkpoint inhibitors plus chemotherapy in SCLC." (PMID 41187938, 2025). "Through a comprehensive workflow combining H3K27ac-ChIP-seq and RNA-seq analyses, we identified critical TFs and tumor-specific super-enhancer domains (T-SEDs) that regulate gene expression in HPV+ HNSCC, such as TP63, SMAD3, FOSL2, JUND, JUNB, KLF5, and TFAP2A." (PMID 41323280, 2025). "Although one βA subunit in this mutant can still be cleaved by furin to generate A70 and induce significant SMAD3 signaling when secreted by Furin wild-type cells in vitro, it failed to mediate a tumor growth advantage or disadvantage in vivo." (PMID 40064965, 2025). "IHC results indicated that siTGF-β1@ILP, modified with cetuximab, achieved active targeting, significantly enhanced the enrichment and gene silencing effects of siRNA in tumor cells, and exhibited strong inhibitory effects on TGF-β1 and p-Smad3 protein expression." (PMID 39940962, 2025). "Furthermore, ATOH8 has been found to bind with SMAD3, forming a transcriptional complex that activates the TGF-β signaling pathway, induces cellular senescence, and suppresses tumor transformation." (PMID 40282270, 2025). "TGF-β1 activates the SMAD3 and ERK1/2 signaling pathways, inducing neutrophils in the tumor microenvironment to express tumor-promoting factors, such as OSM and VEGFA mRNA, thereby converting neutrophils into a pro-tumor phenotype." (PMID 40564191, 2025). "SMAD3, a central mediator of the TGF-β signaling pathway, exhibited significant upregulation in advanced-stage LUAD compared with early-stage disease, correlating with increased tumor aggressiveness and poor patient outcomes." (PMID 40361382, 2025).
tumor (continued). "Finally, the levels of genes involved in the tumor EMT, such as CDH2, CDH11, SMAD2, SMAD3, WNT9A, and SP-1, were significantly downregulated after the SH intervention." (PMID 41444284, 2025). "Furthermore, pathways involved in tumour invasiveness and metastasis were also connected and presented in pLN+ OSCC, including clusters named ‘MET promotes cell motility’ and ‘SMAD2/SMAD3:SMAD4 heterotrimer regulates transcription’." (PMID 40038875, 2025). "Smad molecules, such as R-Smads (Smad2, Smad3) and Co-Smad (Smad4), are central mediators of the canonical TGF-β pathway and play critical roles in effectuating TGF-β-mediated EMT, leading to tumor progression." (PMID 39518973, 2024). "The results of RT-qPCR and Western blot demonstrated an enhancement in the mRNA and protein expression of SMAD3, ITGA6, PI3K protein expression and Akt phosphorylation level yet unchanged total Akt protein expression in the tumor tissues of mice treated with H460/oe-SMAD3 + Gy or H460/CAFs + Gy." (PMID 38493128, 2024). "Interestingly, blocking the Smad signaling pathway, by means of Smad3/4 CRISPR KO, significantly increased both tumor volume and tumor mass compared to the non-targeting control (scrambled) and parental cell (A375m) groups." (PMID 38201651, 2024). "This does not necessarily mean that Smad3 has no tumor suppressive effects, which are highly context-dependent." (PMID 38569937, 2024). "Moreover, IHC analysis conducted on tumor tissues from PDX models also demonstrated a decrease in p-ERK, and p-SMAD3 levels following treatment with domperidone." (PMID 38528618, 2024). "Importantly, we demonstrated that Runx1 was Smad3‐dependently up‐regulated in the TGF‐β1‐stimulated BMDMs in vitro and MMTs of LLC‐tumor in vivo." (PMID 37967345, 2024). "MST1 was related to age (P = 0.002) and tumor size (P = 0.007), YAP expression was related to gender, smoking, and grade (P = 0.033, 0.033, 0.006, respectively), SMAD3 was related to family history and grade (P = 0.004, ˂ 0.001), LATS2 was related to age (P = 0.024)." (PMID 38589525, 2024). "CHI3L1 may promote tumor growth and migration by interacting with TGF-β1 and TGFR, thereby activating the SMAD2/SMAD3 signaling pathway." (PMID 38177294, 2024). "SMAD family member 3 (SMAD3), a modulator of the neural lineage differentiation of pluripotent NSCs, served as a key regulator for the genetic promotion of the MNT, and its blockage reduced tumor innervation and tumor-related nociceptive behaviors in vivo." (PMID 38334648, 2024). "In our previous studies, we found that propranolol could reverse norepinephrine-induced tumor cell EMT through the modulation of β-AR/TGF-β1/HIF-1α/Snail and β-AR/TGF-β1/p-Smad3/Snail pathways." (PMID 38294713, 2024). "For example, piR-25783 activates the TGF-β/Smad2/Smad3 pathway in fibroblasts by increasing Smad2 and Smad3 phosphorylation, promoting the fibroblast-to-myofibroblast transition (FMT) process and enhancing the proliferative and metastatic properties of tumor cells." (PMID 38915084, 2024). "Targeting TGFB1/SMAD3/RUNX1 signaling inhibits MMT-driven CAF and tumor formation in NSCLC." (PMID 39201328, 2024). "Smad3 knockout mice are resistant to PMA-induced skin carcinogenesis, and this effect may involve the reduction of macrophage infiltration into tumor tissue in Smad3 knockout mice." (PMID 38569937, 2024). "Overexpression of SMAD3, SMAD4, and SMAD5 indicates excessive stimulation of the TGFβ pathway, which may promote tumor proliferation and development." (PMID 39337574, 2024). "In addition, the expression of the SMAD3 and PITX1 downstream targets can accurately segregate GB from LGG in a panel of >600 TCGA tumour samples." (PMID 37833281, 2023). "Immunohistochemical staining revealed that the expression of the phosphorylated Smad3 was significantly reduced in the ELNV and ELNV + Laser groups, suggesting that ELNV effectively blocked the TGF-β/Smad signaling pathway in tumor tissues." (PMID 37328484, 2023).
tumor (continued). "Neutrophil depletion, which was validated by immunostaining in tumor tissues, resulted in a marked increase in tumor growth in Smad3-KO mice, but did not affect tumor growth in wild-type controls." (PMID 37002229, 2023). "In addition, SMAD3 upregulation, by inducing STYK1 expression, promotes cell invasion migration and the EMT process and enhances tumour cell resistance to paclitaxel." (PMID 37685308, 2023). "High-risk tumor depths (≥4 mm) demonstrated a markedly significant negative dependence on both phosphorylated SMAD2 (C.C −0.214; p = 0.001) and SMAD3 (C.C −0.200; p = 0.002), which is consistent with a tumor-suppressive role for SMAD2/3 activators in cSCC." (PMID 36980718, 2023). "Studies have reported that FOSL2 can interact with Smad3, Wnt5a, or SNAI2 to promote tumour growth." (PMID 37380804, 2023). "Although the presence of chemokines such as CCL2 may lead to SMAD3 phosphorylation, using a TGF-β1 receptor specific inhibitor, we confirmed that tumor-secreted TGF-β1 is solely responsible for the pSMAD3 response in TCM-treated cells." (PMID 37682817, 2023). "SMAD3-activation of the TGF-ß/Smad3 pathway, which jointly targets ABR and LPAR5, could alter tumor cell function in PTC by suppressing NIS expression and altering tumor cell function." (PMID 37324256, 2023). "Also, the high expression of miR-92b directly downregulates SMAD3 expression and inhibits the TGF-β/SMAD3/p21-mediated reduction in tumour cell growth." (PMID 37891744, 2023). "While LLC tumors showed p-Smad3 staining in Smad3-KO mice, this staining was absent from Ly6G+ TANs and was attributed to Smad3 activation within LLC tumor cells." (PMID 37002229, 2023). "The tumor suppressor function of SMAD2 and the pro-tumorigenic role of SMAD3 have already been demonstrated in various models, but only a few studies have been conducted to assess the selective importance of SMAD2 vs. SMAD3 in cancer progression." (PMID 35681731, 2022). "Furthermore, consistent with tumor suppression, combination therapy significantly reduced p-SMAD3 and CBP levels in xenograft tumor mouse models compared with single-agent treatment." (PMID 35982471, 2022). "Despite Smad3 plays crucial role as a tumor suppressor, recent reports suggest that no embryonic lethality was promoted when Smad3 gene was silenced or knockout." (PMID 35295334, 2022). "We found that mice lacking Smad3 and receiving systemic Smad3 inhibitor treatment are protected against tumor growth, invasion, metastasis, and death on syngeneic mouse models in vivo." (PMID 36206343, 2022). "In addition, SMAD3 is a key mediator of canonical TGF-β signaling, which is known to influence tumor progression via regulating cancer cells infiltration, adhesion, EMT and extracellular matrix degradation." (PMID 35291909, 2022). "Notably, the CRC members identified include the retinoic acid receptor homologs RARA, RARB and the tumour suppressors HIC1 and SMAD3." (PMID 36147741, 2022). "Interestingly, Recent studies show that the biological function of SMAD3 opposes that of SMAD2 in tumor metastasis, and silencing SMAD2 promotes tumor metastasis, whereas SMAD3 KO inhibits tumor metastasis." (PMID 35085106, 2022). "Subsequently, p-Smad2 and p-Smad3 enter the nucleus to regulate the transcription and expression of corresponding target genes, which induce the EMT and enhance the migration and invasion of tumor cells in the final." (PMID 35578690, 2022). "To conclude, the molecular assessment of SNU1544 and LS174T 3D tumor lysates indicated that treatments with 177Lu-DOTA-M5A and/or onalespib could possibly restore SMAD3 expression in the TGF-β pathway." (PMID 35433442, 2022).
tumor (continued). "Therefore, SMAD3 partners with TCF1 transcription factor to impose CD8+ T cell exhaustion and subsequent dysregulation of anti-tumor immunity." (PMID 35915084, 2022). "Importantly, macrophage‐specific silencing of Smad3 effectively prevented MMT, resulting in a significant reduction in CAF and tumor regression in vivo." (PMID 34791825, 2022). "The results indicated that the regulations of P-AKT, P-PI3K, Smad2, Smad3, P-JNK, P-ERK, and NF-κB expressions may be involved in resveratrol enhances anti-tumor of cisplatin in MDA231 xenografts." (PMID 33921192, 2021). "The analyses of the SMAD3 signature in tumor samples highlighted the tumor heterogeneity (mRNA expression level of genes forming the SMAD3 signature is variable between patients, and all genes forming the SMAD3 signature are not high in each tumor)." (PMID 33724679, 2021). "Evidences have found that activation of TGF-β/Smad3 signaling pathway could promote the metastasis and EMT in tumor cells." (PMID 34324434, 2021). "Consistently with these observations, SMAD3 knockdown increased E-cadherin expression, downregulated Vimentin, and reduced cell migration cells in vitro, as well as prevented TGFβ-induced EMT in SMAD4-expressing tumor cells." (PMID 34680235, 2021). "The noncanonical phosphorylation of SMAD3 by CDKs 2 and 4 leads to the inhibition of tumor-suppressive function of SMAD3." (PMID 34771508, 2021). "Furthermore, while PLEXIND1 potentially engages SMAD3 and NRP1 to mediate tumor growth in BxPC-3 cells, the involvement of RAC-1 and KRAS is unclear." (PMID 34439202, 2021). "Although polyI:C transfection did not significantly affect tumor volume, tumor weight was significantly reduced by polyI:C transfection and phosphorylation of Smad3 in tumor samples was significantly reduced after polyI:C transfection." (PMID 33342034, 2021). "SMAD2 knockdown effectively increases this effect of SMAD3/4, and inducing the transcription of SMAD7 may prevent TGF-β-induced EMT of tumor cells; thus, SAMD7 and SAMD2 may play a role in EMT to regulate tumor metastasis." (PMID 34367975, 2021). "The present study analyzed the data from TCGA in Ocomine database and the results revealed that SMAD3 was highly expressed in tumor tissues compared with normal tissues (data not shown)." (PMID 33758603, 2021). "Finally, we used western blot analyses with total protein lysates of the tumor tissues to show a significant increase in phosphorylation levels of AKT, SMAD3, and ERK1/2 in tumors derived from the MDA-MB-231 and 4T1 cells re-expressing W3-WT but not W3-Y4." (PMID 33012785, 2020). "Therefore, we conducted a longitudinal study of the gut microbiota in the Smad3-/- mouse CAC model, focusing on early time-points to better understand the complex relationship of the gut microbiota, chronic inflammation, and tumor development." (PMID 32706816, 2020). "Prompted by our hypothesis that RAC1B was a tumor suppressor, we considered the possibility that RAC1B-driven SMAD3 expression fulfills an as-yet-unknown anti-oncogenic function." (PMID 33266416, 2020). "MSI2 can regulate tumour progression through PTEN, Smad3, TGF-β, LRIG1 and others." (PMID 32606289, 2020). "Finally, compared to macroH2A1 KD Huh-7 cells, FAK KD cells exhibited a significant reduction (p < 0.01) in the mRNA levels of tumor-promoting genes CCL2, EGF, BAX, KRT19, EGFR, NOTCH1, ABL1, and SMAD3." (PMID 33182805, 2020). "It has been reported that intracellular IL-37b can interact with Smad3 to suppress multiple signaling pathways (such as ERK, p38 MAPK, JNK, PI3K, NF-κB, and STAT3 pathways) and modulate the expression of metastasis-related genes in tumor cells." (PMID 32226541, 2020).
tumor (continued). "However, according to recent studies, Smad3—a tumor-promoting factor—can increase VEGF expression and promote tumor angiogenesis, and Smad2—a tumor-suppressing factor—can inhibit tumor metastasis and angiogenesis." (PMID 32993787, 2020). "They found higher degree of methylation of MGMT, RARβ, RASSF1A, and CDH13 in tumour specimens and of SOCS-1 in peripheral blood with higher levels of IL-6, while others found less degree of methylation of USP2, TMEM49, SMAD3, DTNB, and IL-6 promoter with higher levels of IL-6." (PMID 31205673, 2019). "These bioinformatics results implicate that SMAD2, SMAD3 and SMAD4 may exert tumor suppressive functions in the prostate, including the inhibition of ETV1’s oncogenic activity." (PMID 31160676, 2019). "Particularly, ONECUT2 is overexpressed in poorly differentiated neuroendocrine prostate tumors, and its expression increases with tumor progression; in tumor cells, ONECUT2 acts as a regulator of hypoxia signaling and regulates HIF-1α binding to chromatin through SMAD3 activation." (PMID 31366128, 2019). "Based on our results, for the first time, we can state that tumor suppressive TGF-β signaling pathway is dependent on Smad2 mediated activities and pro-oncogenic TGF-β signaling may dependent on Smad3 mediated activities." (PMID 31798766, 2019). "Thus, its tumor suppression activity is abolished due to disruption in CDKN1A and SMAD3 pathway which is related to cell cycle regulation and aberrant activation of PI3K/AKT pathway." (PMID 30057548, 2018). "The binding of Smad2 or Smad3 and VEGF-C promoter was demonstrated in tumor cells." (PMID 30142879, 2018). "In addition, IHC for p-Smad2, p-Smad3 and p-c-Myc was performed on the tumour edge tissues of the PIM1 knockdown mice and control mice to confirm tumour invasiveness." (PMID 29472550, 2018). "Native Smad3−/− mice (without tumour inoculation) showed slight increase in mature NK1.1+ CD49b+ NK cells in the bone marrow, spleen, lung and peripheral blood compared with Smad3+/+ mice." (PMID 28262747, 2017). "We showed that miR-1 inhibited tumor proliferation by suppression of glycolysis and negative regulation of Smad3 activity and HIF-1α expression." (PMID 28471448, 2017). "Importantly, SMAD4, SMAD3, and other key components of the TGF-β/SMAD signaling pathway (i.e., TGFβr1, TGFβr2, and SMAD2) are found within exosomes isolated from tumor cell lines and from human plasma samples." (PMID 28060758, 2017). "We have also shown that CDK2 inhibition can block non-canonical Smad3 phosphorylation, resulting in restoration of the tumor-suppressor role of Smad3 in TNBC." (PMID 29137393, 2017). "Especially in the responder tumor overexpressed transcripts include the growth factors TGFB1 (log 2fc=−2.07) and TGFB1/1 (log 2fc=−3.27) themselves, as well as their direct pathway targets SMAD3 (log 2fc=−2.44) and SMAD7 (log 2fc=−3.86)." (PMID 28594404, 2017). "The effect of Smad3−/− microenvironment on NK cell production was confirmed on a B16F10-rechallenged model, where increased NK1.1+ NKp46+ NK cells were observed in the tumour tissue, blood and spleen of rechallenged Smad3−/− mice compared with the rechallenged Smad3+/+ control." (PMID 28262747, 2017). "A 10-fold increase in the number of tumour-infiltrating NK1.1+ NKp46+ and NK1.1+ IFN-γ+ NK cells was found in the B16F10 tumour-bearing mice lacking Smad3 compared with the Smad3+/+ group." (PMID 28262747, 2017). "Interestingly, comparing to the study with transfer of Smad3−/− T-bet knockdown NK cells, adoptive transfer of Smad3−/− E4BP4 knockdown NK cells significantly promoted tumour growth in NOD/SCID mice with lower levels of IFN-γ production." (PMID 28262747, 2017). "In addition, CCL2-mediated activation of SMAD3 and the MAPK pathway are involved in the increased survival of tumor cells and an enhanced metastatic phenotype of these cells." (PMID 28143493, 2017).